INS (insulin)
Diseases named in the same sentence as INS in open-access papers (continued):
Sharing a sentence is not in itself a finding about the gene and the disease.
Hypoglycemia (continued). "In spite of structural homology with insulin, normal levels of IGF-2 do not cause hypoglycemia." (PMID 24934576, 2014). "Patients in the OAD plus insulin group were more likely to report ≥1 hypoglycemia symptom (83.3% [244/293]) compared with those in the sulfonylurea without insulin group (69.9% [172/246]) or the nonsulfonylurea OAD without insulin group (59.1% [162/274]; P < 0.001)." (PMID 25433668, 2014). "Hypoglycaemia is not a common presenting feature of AD regardless of the presence of T1DM, although it has been associated with both primary and secondary glucocorticoid deficiency as a result of an enhanced insulin sensitivity." (PMID 25214204, 2014). "Since denervation of the glands prevented the action of insulin, de Castro concluded that the discharge of adrenalin was controlled by the central nervous system, and neither insulin nor the resulting hypoglycaemias have a direct effect on adrenomedullary cells." (PMID 24860435, 2014). "This hypothesis is further supported by the reduction in length and severity of hypoglycaemia when the patient was anti-insulin antibody negative." (PMID 24711924, 2014). "Since ID treatment results in more stable insulin levels and a greater effect on glucose metabolism in the liver than in peripheral tissues, it has also been suggested that the weight difference between NPH and ID is due to a reduced frequency of hypoglycemia with ID." (PMID 24739875, 2014). "There were significant increases in the risks of macrosomia (RR, 2.34; 95% CI, 1.18–4.63, p = 0.03) and neonatal hypoglycemia (RR, 2.06; 95% CI, 1.27–3.34, p = 0.005) in the glyburide group compared to insulin whereas results for the other analyzed outcomes remained non-significant." (PMID 25302493, 2014). "Furthermore, the period when insulin was not required became shorter and was followed by long periods of hypoglycaemia." (PMID 24711924, 2014). "It is tempting to speculate about a link between trends in insulin therapy and hypoglycemia reduction, but our study was not designed to investigate effects of different treatment modalities on hypoglycemia risk." (PMID 25289645, 2014). "The basal insulin dosage was significantly decreased in the MDI group compared with that in the CSII group, but the CSII group was superior to MDI group in decreasing fasting blood glucose and shortening the time required for hypoglycemia to meet the targeted level." (PMID 25187822, 2014). "Thus, intestinal expression of Pdx1, MafA, and Ngn3 drives the formation of ectopic insulin-producing cells that confer an improved response to glucose challenge without fasting hypoglycemia." (PMID 24613355, 2014). "Both early and late insulin infusions maintained cortisol elevated for the remainder of the sampling time, reaching a peak of approximately 200% suggesting that the adrenal responsiveness to hypoglycemia is not impaired with fasting duration." (PMID 23997935, 2013). "Finally, in RH rats pre-treated with NAC (0.5% in drinking water for 9 days) hypoglycemia-induced VMH ROS production was prevented and glucagon and epinephrine production was not blunted in response to subsequent insulin-hypoglycemia." (PMID 23894333, 2013). "Compared to the traditional methods of insulin therapy by means of multiple daily insulin injections (MDI), CSII can significantly decrease glycated hemoglobin (HbA1C), reduce 24-hour glucose variability, decrease incidence of severe hypoglycemia, and eliminate dawn phenomenon." (PMID 24347835, 2013). "Additionally, significantly more patients using exenatide QW compared to sitagliptin, pioglitazone, or insulin glargine attained the composite goal of HbA1c <7% or ≤6.5%, without weight gain or hypoglycemia." (PMID 23522121, 2013). "Importantly, the rate of severe hypoglycaemia in subjects on such agents was low and there were no documented hypoglycaemia episodes among subjects not on insulin or a sulphonylurea agent." (PMID 23464594, 2013).
Hypoglycemia (continued). "Insulin dose adjustment is another approach to avoiding hypoglycaemia around exercise, and a reduction in insulin dosage may account for the absence of a reduction in HbA1c." (PMID 23554942, 2013). "The authors explained the discrepancy between the ability of S-21663 to stimulate insulin secretion at all levels of glucose and the lack of hypoglycemia seen in vivo by the existence of some compensatory mode of action by this compound in vivo, but not seen in vitro." (PMID 27429837, 2012). "Persistent suppression of α-cell response may result in defective glucose counterregulation, leading to insulin-induced hypoglycemia, as a consequence of lacking hepatic glucose production under glucagon-stimulated conditions." (PMID 23316165, 2012). "Three RCTs explicitly mentioned providing intravenous glucose supplementation to patients who were not receiving any other nutrition; in contrast to most other studies, intensive insulin did not significantly increase the incidence of hypoglycemia in these trials (RR 1.64, 0.56 to 4.80, P = 0.37)." (PMID 23082798, 2012). "Moreover, 67% of patients in the liraglutide-added group who achieved the composite endpoint of HbA1c ≤ 7.0% with no weight gain and no hypoglycemia, this was significantly higher than 19% of patients in the insulin-increasing group." (PMID 23153177, 2012). "Thus, the occurrence of hypoglycaemia, when carefully managed, did not preclude intensification of insulin therapy." (PMID 22413808, 2012). "The original human insulin-based products, such as NPH insulin, had suboptimal pharmacokinetic (PK) profiles, characterised by inappropriate peaks of action coupled with high variability from injection to injection, both of which can lead to hypoglycaemia and oblige twice-daily dosing." (PMID 22485010, 2012). "Multivariable adjusted positive predictors of incident hypoglycaemia over the follow-up were prior anamnestic hypoglycaemia, retinopathy, depression, insulin use and blood glucose self-measurement, but not sulfonylurea use as previously reported for anamnestic or recalled hypogylcaemia." (PMID 23075070, 2012). "We did not observe a burst release of insulin when the particles were triggered with glucose concentrations analogous to hypoglycemia (5 mmoles/L, ∼90 mg/dL) and normoglycemia (7 mmoles/L, ∼126 mg/dL), suggesting that the AVTs are suitable for maintaining normal blood glucose levels." (PMID 22272238, 2012). "However, the percentage of subjects reaching the composite endpoint of HbA1c ≤ 7.0% with no weight gain and no hypoglycemia, was significantly higher in the liraglutide-added group than in the insulin-increasing group (67% vs. 19%, p<0.001)." (PMID 23153177, 2012). "Rats were subjected to moderate hypoglycemia by insulin without anesthesia." (PMID 22830525, 2012). "In addition, there was a decreased frequency of hypoglycemia and no weight gain in the group using insulin detemir compared to the NPH group which did have some weight gain." (PMID 22067102, 2011). "Spontaneous hypoglycemia without insulin therapy might be even more dangerous, resulting in a 1.7-fold increase in mortality, because it is often detected late, furthermore, the duration of the episodes are longer due to less frequent monitoring than with IIT." (PMID 21470423, 2011). "Although it could be degraded into insulin once administered, the window of safe doses not engendering hypoglycemia could be wider." (PMID 21647401, 2011). "There were no documented cases of hypoglycemia in patients receiving insulin infusions." (PMID 20811546, 2011). "Importantly, exenatide therapy does not increase the risk of severe hypoglycemia when used in the absence of agents commonly associated with hypoglycemia, primarily SFU and insulin." (PMID 21410975, 2011).
Hypoglycemia (continued). "In conclusion, Cƒ2-B may have no direct stimulatory effects on insulin secretion, and may produce hypoglycemia through an extra-pancreatic mechanism, probably by increasing peripheral utilization of glucose by the tissues." (PMID 21544041, 2011). "For example, if a patient is treated with prednisone for an asthma exacerbation and the steroid dose is lowered but the insulin dose is not lowered, hypoglycemia may occur the next day." (PMID 23882328, 2011). "In our study, in which hypoglycaemia cannot be reliably assessed, glucose control was better with insulin glargine compared with NPH as might be expected if experience of hypoglycaemia limits insulin dose titration in regular clinical practice." (PMID 20946269, 2010). "The type of insulin for inducing hypoglycemia does not influence QT prolongation." (PMID 21234404, 2010). "Furthermore, males and females recovered equally well from insulin-induced hypoglycaemia (data not shown)." (PMID 20863371, 2010). "In the present study, enhanced muscarinic M1 and M3 receptor binding in the cerebellum of insulin induced hypoglycemia in both diabetic and nondiabetic rats along with increased AchE activity and decreased ChAT expression shows altered acetylcholine metabolism in the cerebellum." (PMID 20137086, 2010). "This raises a possibility that GK expression might be modulated by insulin or another unidentified factor rather than hypoglycaemia per se." (PMID 19442093, 2009). "Regardless of their prior basal insulin regimen, switching to BIAsp 30 – bid in the majority of cases – enabled many patients in this international cohort to achieve the HbA1c target without hypoglycaemia." (PMID 19504715, 2009). "However, there was no statistical correlation between the number of insulin injections per day and the incidence of hypoglycaemia (p = 0.899) or SH (p = 0.378)." (PMID 18489577, 2008). "However, in a previous study with the Aalst Glycemia Insulin Protocol, a dynamic algorithm that adapts insulin dosage to intrinsic insulin sensitivity and changes in BGL over time, hypoglycemia (BGL < 50 mg/dL) occurred only in 0.7% of patients, with 40 mg/dL as lowest value." (PMID 19055829, 2008). "Similarly, in a series of nondiabetic poisoned patients presenting with toxic hypoglycaemia, fewer than 1% had self-injected insulin." (PMID 17963523, 2007). "Other studies have measured GH secretion after stimulation with GH-releasing hormone or insulin-induced hypoglycemia rather than assessing spontaneous, diurnal GH secretion (as in this study), rendering any comparisons and subsequent conclusions between the studies difficult." (PMID 17662149, 2007). "Importantly, since the rate of insulin infusion and the resulting hyperinsulinemia was identical in both T1DM patients and control participants, this factor cannot explain the difference in awakenings to hypoglycemia between the groups." (PMID 17326710, 2007). "Insulin level is not related to the severity of hypoglycaemia." (PMID 17963523, 2007). "Interestingly, as in our study, the dose and type of insulin were found to be closely related to the duration but not to the severity of hypoglycaemia." (PMID 17963523, 2007). "Indeed, many of the predisposing factors for hypoglycemia in patients in the ICU are easily recognizable by ICU nurses, such as worsening nutritional status without adjustment for insulin infusion." (PMID 17147466, 2006). "Further analyses suggested that the reduced Negative Well-being among insulin-treated patients may be entirely attributable to the experience of hypoglycaemia in this treatment group." (PMID 16817960, 2006). "Patients with MEN1 often present with multiple pNETs, which may exhibit multihormonal secretion and frequently cosecrete GHRH and insulin in MEN1, while hypoglycemia may not be manifested possibly due to GH and insulin's counteractive effects on glucose metabolism." (PMID 42007244, 2026).
Hypoglycemia (continued). "Additionally, the fact that SGLT2 inhibitors do not exert effects in the hypoglycemic range suggests that insulin administration may play a primary role in the occurrence of hypoglycemia." (PMID 40828947, 2025). "A point that merits consideration is that the current in vitro metabolic fuel deficiency paradigm is not an exact replication of pathophysiological exogenous insulin-induced reductions in brain tissue glucose levels in vivo that may result from iatrogenic hypoglycemia." (PMID 41451136, 2025). "In this study, the time to peak of premixed insulin lispro 25 was only 0.5–2 h, and the duration of action time was approximately 3–5 h, indicating that it could quickly take effect on elevated glucose after eating food without concerns of late hypoglycemia." (PMID 40070573, 2025). "Finally, in patients on multi-injection insulin therapy, a RCT demonstrated that treatment with IDegLira was responsible for a reduction in HbA1c comparable to MDI, with statistically significant lower rates of hypoglycemia; body weight decreased with IDegLira and increased with MDI." (PMID 39235480, 2025). "Similarly, the coadministration of long-acting insulin with intravenous insulin in pediatric patients decreased the duration of insulin infusion (68.5 vs. 72 hours; p = 0.0001) and reduced hypoglycemia events (12 vs. 22; p = 0.029) without increasing hypokalemia risk." (PMID 41262789, 2025). "Thus, moderate physical activity in individuals with T1D may be useful not only to improve glycemia but also to increase insulin sensitivity without risking hypoglycemia." (PMID 39998445, 2025). "Trials of combining insulin with other drugs to control T2D (GLP-1 RA, DDP-4i, and SGLT2i) suggest that such treatment could lead to the use of reduced doses of insulin, less weight gain, and fewer episodes of hypoglycemia compared with the insulin monotherapy." (PMID 41012462, 2025). "Hypoglycemia did not modify VMNdm Ghrh/SF-1 nerve cell Ghrh transcript levels in either sex, but Ghrh-R siRNA pretreatment had contrary effects on hypoglycemic patterns of Ghrh transcription, namely up- versus down-regulation in INS-injected male versus female rats." (PMID 40688570, 2025). "However, non-therapeutic exposure to insulin can lead to life-threatening hypoglycemia." (PMID 41303503, 2025). "In people, the development of postoperative hypoglycemia is associated with increased morbidity and mortality, but glycemic control is considered standard of care in people, and therefore, the etiology of hypoglycemia may be different (i.e., disease rather than insulin‐induced)." (PMID 41368848, 2025). "ALA can induce insulin autoimmune syndrome (IAS; also known as Hirata’s disease), characterized by hypoglycemia, high concentrations of immunoreactive insulin, and high titers of antibodies to endogenous insulin, even without prior exposure to exogenously administered insulin." (PMID 40699801, 2025). "However, if glucagon can be used not only to prevent and treat hypoglycaemia but primarily to improve the performance of SC CGM and SC absorption of insulin, this new, innovative and disruptive use of glucagon may fulfil the dream of a true, fully automated AP suitable for most patients with DM1." (PMID 37715091, 2024). "Finally, T2DM management should be individualized to minimize hypoglycemia and falls and to avoid agents that may have negative skeletal effects (eg, insulin therapy, sulfonylureas, thiazolidinediones, and canagliflozin)." (PMID 38887632, 2024). "However, another study using an in vivo dialysis system to measure the release rate of catecholamines and substance P from the adrenal gland in rats in response to various stressors had shown that insulin-induced hypoglycaemia did not alter the release rate of substance P from the adrenal gland." (PMID 38392992, 2024).
Hypoglycemia (continued). "If the insulin dose is minimal, it may be possible to discontinue insulin and switch to medications such as alpha-glucosidase inhibitors, dipeptidyl peptidase-4 (DPP-4) inhibitors, and glucagon-like peptide-1 receptor agonist (GLP-1RA)to manage blood sugar levels while also preventing hypoglycemia." (PMID 39575003, 2024). "Furthermore, insulin coordinating inhibition of insulin signaling through MFGE8 provides a physiological feedback mechanism to prevent the possibility of persistent and/or excessive activation of insulin receptor signaling which can lead to life-threatening hypoglycemia." (PMID 38199575, 2024). "However, our patient had no clinical signs indicative of this, with symptoms since childhood, no history of hypoglycemia during fasting, no significantly low blood glucose levels (<2.5 mmol/L) during the test, and no impressively increased insulin-to-glucose ratio." (PMID 39659391, 2024). "Compared whether the oral combination of an SGLT2 inhibitor (DAPA) and a DPP4 inhibitor (SAXA) could achieve similar glycemic control to basal insulin in T2DM patients poorly controlled with metformin, without causing an increase in hypoglycemia or body weight." (PMID 39618646, 2024). "Therefore, mildly elevated HbA1c levels, absence of classical symptoms and frequent insulin-induced hypoglycaemia may be clinical features of TNDM in FBS patients." (PMID 38365697, 2024). "However, these responses can be blunted, and glucagon secretion during insulin-induced hypoglycemia is usually impaired, if not completely absent, thereby raising the question as to whether the α cell is an accessible target to reduce hypoglycemic risk." (PMID 37166980, 2023). "This nationwide cohort study demonstrated that patients with coexisting T2D and COPD requiring insulin therapy might increase the risk of hospitalization for COPD, bacterial pneumonia, ventilation use, and severe hypoglycemia; however, it did not increase the risk of death." (PMID 37242426, 2023). "Additionally, continuous glucose monitoring system use may change patients’ hypoglycemia avoidance behaviors and, when used in combination with an insulin pump, may improve treatment satisfaction, but we did not assess this effect in this study." (PMID 37247225, 2023). "Therefore, we believe that drugs, rather than insulin, decrease hypoglycemia and hyperlipidemia." (PMID 38027146, 2023). "In addition, it was not possible to evaluate the total daily dose of insulin used, preconception HbA1c values and other parameters of glycemic control, such as time in range and the presence of hypoglycemia during pregnancy, since a small portion of patients had access to CGM in this sample." (PMID 37364140, 2023). "Therefore, the primary aim of this manuscript is to summarize the current knowledge of hypoglycaemia in CPSS patients, and the secondary aim of this review is to go deeper into glucose metabolism in CPSS, which in turn enhances our understanding of the liver’s role in glucose and insulin physiology." (PMID 37664849, 2023). "It has been shown that islet transplantation with the use of the Edmonton protocol could successfully restore long-term endogenous insulin production and prevent severe hypoglycaemia in subjects with type 1 DM, but insulin independence was usually not sustainable." (PMID 37176684, 2023). "In the late postprandial period, due to the low affinity of insulin autoantibodies to insulin, excess insulin does not bind to the insulin autoantibodies, and the free insulin exerts its inherent hypoglycemic effect, resulting in a sharp drop in blood glucose and late postprandial hypoglycemia." (PMID 36844104, 2023). "Our findings might be slightly higher than those of other observational studies reporting hospitalizations or emergency department visits for hypoglycemia of 0.2 (patients treated without insulin or sulfonylurea) to 2.0 (insulin or sulfonylurea users) per 100 person-years." (PMID 37046876, 2023).